USO1 (USO1 vesicle transport factor)
Description:
General vesicular transport factor required for intercisternal transport in the Golgi stack; it is required for transcytotic fusion and/or subsequent binding of the vesicles to the target membrane. May well act as a vesicular anchor by interacting with the target membrane and holding the vesicular and target membranes in proximity.
Synonyms: TAP; VDP; p115
Tractability: Antibody: UniProt places it where antibodies can reach, with high confidence. PROTAC: ubiquitination databases record sites on it; its protein half-life has been measured.
Gene: Protein-coding gene on chromosome 4 (75,724,522 to 75,814,290, forward strand). Ensembl gene ENSG00000138768.
Subcellular location: Cytoplasm, cytosol; Golgi apparatus membrane
Subcellular location (Human Protein Atlas): Golgi apparatus; Nucleoli fibrillar center
Pathways (Reactome):
Vesicle-mediated transport: COPI-mediated anterograde transport; COPII-mediated vesicle transport
Cell Cycle: Golgi Cisternae Pericentriolar Stack Reorganization
Gene Ontology:
Molecular function: cadherin binding; protein binding; RNA binding
Biological process: endoplasmic reticulum to Golgi vesicle-mediated transport; membrane fusion; transcytosis; Golgi vesicle transport; intracellular protein transport; vesicle fusion with Golgi apparatus; vesicle-mediated transport
Cellular component: Golgi apparatus; Golgi membrane; membrane; cytosol; endoplasmic reticulum; ER to Golgi transport vesicle membrane; microtubule organizing center; transport vesicle; cytoplasm; perinuclear region of cytoplasm
Genetic constraint (gnomAD): Loss-of-function variants: 55 observed, 106.16 expected, observed/expected ratio (o/e) 0.52, 90% interval 0.42 to 0.65. The upper end of that interval is the gene's LOEUF score, 0.65, which puts it in group 2 of 6, group 1 being the genes least tolerant of losing a copy. Missense variants: 838 observed, 952.42 expected, observed/expected ratio (o/e) 0.88, 90% interval 0.83 to 0.93. Synonymous variants: 349 observed, 331.65 expected, observed/expected ratio (o/e) 1.05, 90% interval 0.96 to 1.15.
Homologues: Orthologues: macaque USO1 (99% identical), chimpanzee USO1 (97% identical), rabbit USO1 (95% identical), dog USO1 (94% identical), mouse Uso1 (92% identical), rat Uso1 (92% identical), pig USO1 (89% identical), guinea pig USO1 (88% identical), tropical clawed frog uso1 (75% identical), zebrafish uso1 (73% identical), Drosophila melanogaster p115 (43% identical), Caenorhabditis elegans uso-1 (31% identical).
Diseases named in the same sentence as USO1 in open-access papers:
USO1 is named in the same sentence as 18 diseases in open-access papers, as found by Europe PMC text mining. Sharing a sentence is not in itself a finding about the gene and the disease. The quoted sentences say what the papers report.
breast carcinoma (4 papers, 2018 to 2023). "The discoveries highlight the pivotal roles that ARF4, COPB1, and USO1 undertake in breast cancer cell proliferation and invasiveness." (PMID 37762375, 2023). "In breast cancer patients, a surge in gene expression linked to ER-Golgi transport processes is evident, exemplified by genes like ARF4, COPB1, and USO1." (PMID 37762375, 2023). "This establishes a role for ARF4, COPB1, and USO1 in the regulation of breast cancer cell growth and invasion through the retrograde transport of proteins from the Golgi to ER via COPI-coated vesicles." (PMID 32426352, 2020). "Together with the upregulation of COPB1 and USO1, which encode for the COPI subunit β1 and General vesicular transport factor p115, respectively and regulate ER-Golgi trafficking, ARF4 has been reported to be upregulated in breast cancer patient samples." (PMID 32426352, 2020). "A comprehensive meta-analysis of breast cancer cells also unravels that the expression patterns of ARF4, COPB1, and USO1 are orchestrated by the CREB3-like transcription factors." (PMID 37762375, 2023). "We found several targets of QKI and RBFOX1, including FLNB, SLK, USO1, ENAH, ESYT2, NUMB and ARHGEF1, to be among the most differentially spliced genes in basal B breast cancer cell lines." (PMID 30059005, 2018).
colon cancer (4 papers, 2019 to 2025). "Knockdown of USO1 (encodes general vesicular transport factor p115) was shown to inhibit cell proliferation and induce cell apoptosis in multiple myeloma cells and colon cancer cells." (PMID 31426369, 2019). "According to these findings, USO1/p115 silencing inhibits colon cancer cell proliferation and migration and promotes colon cancer cell apoptosis, thus suggesting a role for USO1/p115 in colon cancer progression." (PMID 35805075, 2022). "Downregulation of USO1 suppresses cell proliferation and migration, results in early apoptosis and reduces proportion of G2-M phase in human colon cancer cells." (PMID 35449073, 2022). "The deregulation of USO1 decreased colon cancer cells in the G2-M phase." (PMID 40362515, 2025).
multiple myeloma (4 papers, 2019 to 2022). "Recent studies in multiple myeloma have shown that USO1-deficient cells showed have reduced cell proliferation and increased apoptosis via regulation of Erk pathway activity." (PMID 34162911, 2021). "For example, USO1 knockdown inhibits cell proliferation and induces cell apoptosis in multiple myeloma cells." (PMID 35449073, 2022). "Similarly, the USO1/p115 knockdown inhibits proliferation and induces the apoptosis of multiple myeloma cells." (PMID 35805075, 2022).
acute lymphoblastic leukemia (1 paper, 2021). Leukemia with an acute onset, characterized by the presence of lymphoblasts in the bone marrow and the peripheral blood. "To assess whether the gene expression changes caused by USO1-depletion had any clinical relevance, we turned to the Target Phase II Acute lymphoblastic leukemia dataset, accessed via the cBioPortal interface." (PMID 34162911, 2021).
gastric cancer (1 paper, 2025). A primary or metastatic malignant neoplasm involving the stomach. "Previous studies have shown that USO1 is implicated in various tumor types, including hematological malignancies, colorectal and gastric cancer, lung adenocarcinomas (LUADs), and liver cancer." (PMID 40362515, 2025).
leukemia (1 paper, 2021). A malignant (clonal) hematologic disorder, involving hematopoietic stem cells and characterized by the presence of primitive or atypical myeloid or lymphoid cells in the bone marrow and the blood. "Hence, further work to assess the molecular role of USO1 as a putative RBP in MLL-AF4 translocated leukemia is warranted." (PMID 34162911, 2021). "Follow-up studies confirmed a role for USO1, both in cell lines and in a model of MLL-AF4 driven leukemia in primary murine bone marrow cells." (PMID 34162911, 2021). "A recent study reported a KMT2A(MLL)-USO1 fusion gene in a secondary AML, hinting at a further connection between MLL-driven leukemia and USO139." (PMID 34162911, 2021). "Having demonstrated that USO1 is required for the survival and growth of MLL-AF4+ cells in culture, we wanted to determine if USO1 was required in an experimentally induced primary cell model of MLL-AF4-driven leukemia." (PMID 34162911, 2021).
ovarian carcinoma (1 paper, 2025). A malignant neoplasm originating from the surface ovarian epithelium. "We found that the expression of BANF1, CDK2AP2, DDT, LRIG1, MRPL4, and S100A13 was upregulated in ovarian cancer samples, and the expression of EPS8, NUCB2, PAF1, PMP22, RABGAP1L, and USO1 was upregulated in normal samples." (PMID 41000388, 2025).
superficial spreading melanoma (1 paper, 2016). A type of melanoma that typically occurs in light-skinned individuals ranging in age from young adults to the elderly. "Superficial spreading melanoma (SSM) and nodular melanoma (NM characteristically express the eight genes GALNT7, DIS3, FGFR1OP, G3BP2, MTAP, SEC23IP, USO1, and ZNF668." (PMID 27322213, 2016).
cancer (5 papers, 2019 to 2025). A tumor composed of atypical neoplastic, often pleomorphic cells that invade other tissues. "Within these genes, AKAP9, CENPE, PRKCI, RDX, RECQL, and USO1 have also been reported to be associated with cancer progression." (PMID 31426369, 2019). "Studies on the function of USO1 in the development of these cancers have shown that USO1 plays an oncogenic role by promoting cell proliferation, evading apoptosis, and disrupting the cell cycle." (PMID 40362515, 2025). "Some studies have reported that USO1 is involved in the tumorigenesis of certain human malignant tumors." (PMID 35449073, 2022). "USO1 expression is upregulated in several types of cancer including B-ALL with MLL-AF4 translocations." (PMID 34162911, 2021). "Similarly, we also identified differences in isoform usage between KRAS-201 (KRAS4a) and KRAS-202 (KRAS4b), as well as between USO1-201 and USO1-204, which have been reported as functionally relevant in cancer." (PMID 40702779, 2025). "Given the broader range of cancer types that show USO1 dysregulation, our work may have implications beyond those in B-ALL." (PMID 34162911, 2021). "Transcriptome analysis of USO1-depleted SEM cells in our study demonstrated a mixed picture, with the downregulation of certain cancer and cell growth-related pathways, including mTOR and ERB2, but concurrent downregulation of RNA metabolism and MYC targets." (PMID 34162911, 2021).
tumor (3 papers, 2022 to 2025). "Cell proliferation, colony formation, Transwell migration and invasion assay and in vivo tumor formation assay were performed to investigate the roles of Lsm12 and two transcript variants of USO1 in OSCC cells." (PMID 35449073, 2022). "The results revealed that the tumor volume and tumor weight were remarkably decreased in the group of exon 15-deleted USO1, compared with those in the group of full length USO1 (P < 0.01)." (PMID 35449073, 2022). "The analysis revealed that in the training set, the expression of BANF1, CDK2AP2, DDT, LRIG1, MRPL4, and S100A13 was significantly upregulated in tumor samples, and the expression of EPS8, NUCB2, PAF1, PMP22, RABGAP1L, and USO1 was higher in control samples (p < 0.05)." (PMID 41000388, 2025).
infection (2 papers, 2022 to 2025). The state of being infected such as from the introduction of a foreign agent such as serum, vaccine, antigenic substance or organism. "Expression of the general vesicular transport protein p115 (USO1) remains unaltered throughout infection and thus was used as a loading control." (PMID 39772623, 2025). "Some of these interacting proteins play key roles in cytoskeleton organization (FLNB), vesicular traffic (DYNLT1, USO1), and SUMOylation (UBC9) suggesting an interaction of meningococci with these cellular functions during the intracellular phase of the infection cycle." (PMID 35765029, 2022).
USO1 also shares sentences with these, for which no sentence is quoted: B-cell acute lymphoblastic leukemia (1 paper); COVID-19 (1); DiGeorge Syndrome (1); hematological malignancies (1); liver cancer (1); lung adenocarcinoma (1); melanoma (1).